PAX9 (paired box 9)
Description:
Transcription factor required for normal development of thymus, parathyroid glands, ultimobranchial bodies, teeth, skeletal elements of skull and larynx as well as distal limbs.
Synonyms: STHAG3
Tractability: PROTAC: ubiquitination databases record sites on it.
Gene: Protein-coding gene on chromosome 14 (36,657,568 to 36,679,362, forward strand). Ensembl gene ENSG00000198807.
Subcellular location: Nucleus
Subcellular location (Human Protein Atlas): Nucleoli; Nucleoplasm
Gene Ontology:
Molecular function: protein binding; sequence-specific double-stranded DNA binding; DNA-binding transcription factor activity, RNA polymerase II-specific; RNA polymerase II cis-regulatory region sequence-specific DNA binding; DNA binding; DNA-binding transcription activator activity, RNA polymerase II-specific; RNA polymerase II transcription regulatory region sequence-specific DNA binding
Biological process: negative regulation of DNA-templated transcription; regulation of transcription by RNA polymerase II; positive regulation of transcription by RNA polymerase II; regulation of DNA-templated transcription
Cellular component: nucleolus; nucleoplasm; chromatin; nucleus
Genetic constraint (gnomAD): Loss-of-function variants: 6 observed, 27.23 expected, observed/expected ratio (o/e) 0.22, 90% interval 0.12 to 0.44. The upper end of that interval is the gene's LOEUF score, 0.44, which puts it in group 1 of 6, group 1 being the genes least tolerant of losing a copy. Missense variants: 443 observed, 499.79 expected, observed/expected ratio (o/e) 0.89, 90% interval 0.82 to 0.96. Synonymous variants: 217 observed, 218.77 expected, observed/expected ratio (o/e) 0.99, 90% interval 0.89 to 1.11.
Gene-disease validity (ClinGen):
ClinGen rates the evidence that PAX9 causes each of these diseases.
tooth agenesis, selective, 3 (autosomal dominant): Definitive.
Homologues: Orthologues: chimpanzee PAX9 (99% identical), macaque PAX9 (99% identical), mouse Pax9 (99% identical), pig PAX9 (97% identical), rat Pax9 (96% identical), rabbit PAX9 (95% identical), dog PAX9 (90% identical), guinea pig PAX9 (84% identical), tropical clawed frog pax9 (83% identical), zebrafish pax9 (74% identical). Paralogues in human: PAX1 (64% identical), PAX5 (41% identical), PAX2 (40% identical), PAX8 (39% identical), PAX7 (38% identical), PAX3 (36% identical), PAX4 (27% identical), PAX6 (14% identical), VSX2 (13% identical), EVX2 (13% identical), EVX1 (10% identical), ALX4 (10% identical), and 38 more.
Diseases named in the same sentence as PAX9 in open-access papers:
PAX9 is named in the same sentence as 62 diseases in open-access papers, as found by Europe PMC text mining. Sharing a sentence is not in itself a finding about the gene and the disease. The quoted sentences say what the papers report.
tooth agenesis (66 papers, 2009 to 2025). A tooth disease characterized by failure to develop one or more missing teeth. "Hypodontia (dental agenesis) is a genetic disorder, and the mutation C175T in paired box 9 (PAX9) can cause hypodontia." (PMID 41283323, 2025). "The ORs and 95% CIs showed a statistically significant relationship between PAX9 rs2073247 or PAX9 rs2073244 polymorphism and tooth agenesis risk." (PMID 40226363, 2025). "PAX9, a member of the transcription factor family, is associated with autosomal dominant, non-syndromic, and familial hypodontia." (PMID 39183201, 2024). "Tooth agenesis severity appears to be correlated to the effects of these mutations on the DNA-binding capability of the PAX9 protein." (PMID 38473380, 2024). "We also suggested that PAX9 exhibits very high genetic heterogeneity since the same variant can lead to diverse tooth agenesis phenotypes." (PMID 37056289, 2023). "Pathogenic variants in these genes lead to Tooth agenesis (PAX9) and Mega-corpus-callosum syndrome with cerebellar hypoplasia and cortical malformations (MAST1)." (PMID 36651276, 2023). "This allowed us to expand the spectrum of PAX9 mutations and provide a genetic basis for the pathogenesis of congenital tooth agenesis." (PMID 37056289, 2023). "To date, more than 70 PAX9 variants have been reported with varying phenotypes of tooth agenesis, from microdontia and hypodontia to the most common oligodontia." (PMID 37056289, 2023). "As one of the earliest discovered pathogenic genes of tooth agenesis, PAX9 has been a research hotspot." (PMID 35897718, 2022). "In this work, we identified four novel PAX9 variants in Chinese families with non-syndromic tooth agenesis, including two missense variants (p.G64V and p.V117G) and two frameshift variants (p.S119Pfs*2 and p.Y217Lfs*100)." (PMID 35897718, 2022). "There are now 66 PAX9 variations linked to non-syndromic tooth agenesis, with the majority being missense (34/66) and frameshift (21/66) variants." (PMID 35897718, 2022). "Our results broaden the variant spectrum of the PAX9 gene related to non-syndromic tooth agenesis and provide useful information for future genetic counseling." (PMID 35897718, 2022). "Pattern analysis of non-syndromic tooth agenesis caused by PAX9 variants can help with clinical diagnosis, treatment, and genetic counseling." (PMID 35897718, 2022). "The purpose of this research was to investigate and identify PAX9 gene variants in four Chinese families with non-syndromic tooth agenesis." (PMID 35897718, 2022). "Taken together, we report four novel PAX9 variants in non-syndromic tooth agenesis, and our results broaden the variant spectrum of PAX9." (PMID 35897718, 2022). "The goal of this study was to broaden the PAX9 variant spectrum associated with non-syndromic tooth agenesis, investigate the functional implications of newly discovered novel variant loci, and analyze the genotype–phenotype relationships." (PMID 35897718, 2022). "Non-syndromic tooth agenesis caused by PAX9 variants is inherited by autosomal dominant inheritance." (PMID 35897718, 2022). "A heterozygous mutation in either PAX9 or MSX1 has been widely reported to cause tooth agenesis in populations 6,11,13–16." (PMID 33014315, 2020). "Heterozygous mutations in PAX9 have been associated in humans with non-syndromic tooth agenesis, non-syndromic, and familial oligodontia, with peg-shaped laterals and microdontia incisors." (PMID 31708969, 2019). "The proband was screened for mutations of genes previously related to tooth agenesis (i.e., PAX9, AXIN2, EDA, WNT10A, etc.)by targeted exome sequencing (TES), with next generation technology." (PMID 27917906, 2016). "Consistently, the dental mesenchyme-specific transcription factors (Msx1, Pax9, and Lhx6) were decreased in cultured mDMCs, and the mutation of these transcription factors was shown to cause tooth agenesis disorders." (PMID 26925321, 2016).
tooth agenesis (continued). "Since MSX1 and PAX9 are linked to the pathogenesis of nonsyndromic tooth agenesis, we performed detailed mutational analysis of these two genes sampled from Japanese patients." (PMID 25101640, 2014). "Coding mutations within MSX1 and PAX9 have been identified in patients with either nonsyndromic or syndromic forms of tooth agenesis." (PMID 25101640, 2014). "We analyzed the MSX1 and PAX9 nucleotide sequences of 19 Japanese tooth agenesis patients, and thereby identified two novel mutations in the MSX1 gene." (PMID 25101640, 2014). "In contrast to MSX1, both missense and frame-shift mutations in PAX9 have been associated with hypodontia." (PMID 24121910, 2014). "Causative genes, MSX1 and PAX9, can be proposed by the observation that mutations of these genes cause familial and sporadic forms of selective tooth agenesis." (PMID 24319603, 2013). "A spontaneous novel mutation in COL1A2 (c.1171G>A; p.Gly391Ser) causing only dentin defects and a novel mutation in PAX9 (c.43T>A; p.Phe15Ile) causing hypodontia were identified and correlated with the phenotypic presentations in the family." (PMID 23227268, 2012). "Supported by the finding of other PAX9 mutations causing familial tooth agenesis, we conclude that this mutation causes the tooth agenesis in this family." (PMID 23227268, 2012). "Eighteen human mutations of PAX9 have been reported in hypodontia families, of which nine are missense." (PMID 19913215, 2009). "Gene polymorphisms of PAX9 rs2073247 (TT vs CC, CT + TT vs CC) and PAX9 rs2073244 (GG vs AA, AG vs AA, AG + GG vs AA) may increase the risk of non-syndromic hypodontia, and the susceptibility is more obvious in Caucasians and Hungarians." (PMID 40226363, 2025). "Similarly, a mutation in the PAX9 transcription factor has been linked to familial tooth agenesis, also affecting third molars." (PMID 40040530, 2025). "This article concludes that the PAX9 rs2073247 and PAX9 rs2073244 polymorphism might help to increase the risk of tooth agenesis." (PMID 40226363, 2025). "Importantly, mutations in PAX9 and MSX1 have been strongly linked to tooth agenesis, particularly hypodontia and oligodontia; PAX9 is linked to posterior tooth agenesis, while MSX1 is more frequently associated with anterior tooth agenesis." (PMID 40982116, 2025). "Oligodontia and hypodontia have been linked to mutation of PAX9 and MSX1 gene." (PMID 39156431, 2024). "Frameshift and missense mutations in the PAX9 paired domain have been linked to oligodontia, while a missense mutation and an insertion leading to a truncation have been reported in families with hypodontia." (PMID 38473380, 2024). "However, the phenotypes of non-syndromic tooth agenesis caused by variants in PAX9 and MSX1 are different." (PMID 39767847, 2024). "Although studies have focused on the Msh homeobox 1 (MSX1) and paired box 9 (PAX9) genes in the etiology of non-syndromic hypodontia, it is believed that mutations in various gene families may contribute to this condition." (PMID 37865729, 2023). "Hypodontia (dental agenesis) is a genetic disorder, and it has been identified that the mutation C175T in PAX9 could lead to hypodontia." (PMID 37367107, 2023). "When considering isolated cases or the nonsyndromic form, many studies have investigated the correlation between tooth agenesis and genetic mutations present in individuals belonging to one and the same family, attributing the mutations to genes PAX9, MSX1, AXIN2, and EDA." (PMID 25215247, 2014). "Thus, in our whole patient cohort, severe tooth agenesis is explained in altogether 13 patients by mutations in PAX9 and in 11 by mutations in AXIN2." (PMID 23991204, 2013). "Mutations in genes such as PAX9, MSX1, and BMP4 have been associated with tooth agenesis, abnormal dental development, and ectopic eruption patterns." (PMID 40625479, 2025). "Tooth agenesis is typically caused by genetic mutations in MSX1, PAX9, and AXIN2 that affect tooth development." (PMID 40136761, 2025).
tooth agenesis (continued). "Numerous case–control studies have reported the correlation between PAX9 rs2073247, PAX9 rs2073244, and MSX1 rs12532 gene polymorphisms and tooth agenesis." (PMID 40226363, 2025). "In this study, we initially examined the genotype distribution and allele frequency of SNPs of the MSX1, PAX9, and AXIN2 genes that were previously identified in GWAS as being associated with hypodontia susceptibility." (PMID 39183201, 2024). "Tooth agenesis is associated with several genes; however, non-syndromic human tooth agenesis has been associated with mutations in AXIN2, EDA, PAX9, MSX1, and PAX9." (PMID 39156431, 2024). "In this study, we investigated the use of machine learning to predict hypodontia risk based on selected SNPs in the MSX1, PAX9, and AXIN2 genes." (PMID 39183201, 2024). "Our genotype-phenotype analysis suggests that PAX9 variants mainly cause autosomal-dominant NSO, occasionally non-syndromic hypodontia, and seldom correlate with syndromic tooth agenesis." (PMID 37056289, 2023). "In this study, we investigated four candidate genes MSX1, PAX9, AXIN2, and WNT10A in an Iranian family with hereditary non-syndromic tooth agenesis to find the variants responsible for tooth agenesis." (PMID 36561383, 2022). "Mutations in PAX9, MSX1, WNT10A, and AXIN2 genes are most commonly associated with non-syndromic tooth agenesis in the literature." (PMID 36561383, 2022). "Mutations in several genes have been associated with familial tooth agenesis, among others MSX1, PAX9, AXIN2, EDA, EDARADD, and EDAR." (PMID 33743023, 2021). "An interesting case with familial tooth agenesis and spontaneous DGI was reported to be caused by the maternal PAX9 (c.43T>A, p.(Phe15Ile)) and de novo COL1A2 (c.1171G>A, p.(Gly391Ser)) mutations, respectively." (PMID 34201399, 2021). "Mutations of several genes such as PAX9, MSX1, AXIN2, KDF1 and WNT10A have been reported which are associated with non-syndromic tooth agenesis." (PMID 33014315, 2020). "Among several genes involved in tooth development, mutations in MSX1, PAX9, AXIN2, WNT10A, EDA and KDF1 have been reported to play a role in tooth agenesis 6–13." (PMID 33014315, 2020). "Research has identified an association between mutations in MSX1, PAX9, EDA, AXIN2, WNT10A, WNT10B and LRP6 and human tooth agenesis." (PMID 31914153, 2020). "Human genetic studies have identified familial tooth agenesis genes, such as Wnt10a, Pax9, and Msx147–52." (PMID 31492950, 2019). "For instance, genes whose mutations are associated with tooth agenesis, such as MSX1 and PAX9, also contain single nucleotide polymorphisms as genetic risk factors for orofacial clefts." (PMID 30305871, 2018). "Other genes including TGFA, PAX9, FGFRI and IFR6, which had previously been related to oral clefts, were also associated with isolated tooth agenesis, as observed in premolars." (PMID 29167708, 2017). "We sequenced the coding regions of the PAX9 and MSX1 genes from nine patients with non-syndromic tooth agenesis, and identified a missense mutation, P20L, of PAX9 in a single familial case involving three patients in two generations." (PMID 29023497, 2017). "In the present work, we present the analysis of the phenotype and the genotype of the genes PAX9 and MXS1 of six families affected by severe tooth agenesis associated with other dental anomalies and systemic entities." (PMID 24316698, 2014). "At present, mutations causing non-syndromic tooth agenesis have been identified in MSX1, PAX9, AXIN2, EDA, and WNT10A." (PMID 23227268, 2012). "The severe clinical phenotype of the proband could be explained by synergistic overlapping effects of having two mutations together, similar to recently reported cases of familial tooth agenesis with LRP6 and PAX9 mutations." (PMID 39685785, 2024). "In mice, a complete deficiency of Pax9 causes a thymic aplasia and a lack of teeth, while in humans, autosomal recessive mutations in PAX9 cause selective tooth agenesis." (PMID 32431714, 2020).
tooth agenesis (continued). "Transcription factors PAX9 and MSX1 play crucial roles in the development of permanent teeth at the bud stage, and their loss-of-function variants have been associated with congenital tooth agenesis." (PMID 29023497, 2017). "Congenital tooth agenesis is caused by mutations in the MSX1, PAX9, WNT10A, or AXIN2 genes." (PMID 26030286, 2015). "In the present study, we present the analysis of the phenotype and the genotype of six families affected by severe tooth agenesis associated with other dental anomalies and systemic entities, in which mutations of genes PAX9 and MSX1 were not identified." (PMID 24316698, 2014). "To date, mutations in AXIN2 (axis inhibition protein 2), EDA (ectodysplasin A), MSX1 (msh homeobox 1), PAX9 (paired box 9) and WNT10A (wingless-type MMTV integration site family, member 10a) have been demonstrated to be associated with non-syndromic tooth agenesis." (PMID 24278334, 2013). "In general the more severe phenotypes, with more congenitally absent teeth occur, relate to haploinsufficiency of Pax9 while those with mild or moderate hypodontia are associated with hypomorphic alleles." (PMID 19913215, 2009). "Therefore, it is hypothesized that polymorphisms in PAX9 and MSX1 may increase the risk of tooth agenesis in individuals." (PMID 40226363, 2025). "The genetic basis of tooth agenesis is well-established, with several genes identified as controlling factors, namely MSX1, PAX9, AXIN2, EDA, IRF6, FGFR1, and WNT10A." (PMID 40040530, 2025). "Among them, the transcription factors, paired box gene 9 (PAX9) and Msh Homeobox 1 (MSX1), have emerged as genes likely to be responsible for isolated/non-syndromic hypodontia and oligodontia." (PMID 35273362, 2022). "Several genes, including MSX1, PAX9, AXIN2, WNT10A and EDA have been reported to involve in tooth agenesis." (PMID 33014315, 2020). "The nature of this association would be better determined by genetic investigations in humans, taking into consideration the different pathways of PAX9, MSX1, and AXIN2 acting on both hypodontia and delayed dental development." (PMID 26462655, 2016). "PAX9, MSX1, AXIN2, WNT10A and EDA have been experimentally established for congenitally missing teeth like hypodontia and oligodontia." (PMID 25203534, 2014). "As PAX9, MSX1, and AXIN2 are most frequently associated with non-syndromic hypodontia, we studied these specific genes." (PMID 39183201, 2024). "In this family, Sanger sequencing detected no mutations in PAX9, AXIN2, MSX1, or WNT10A, which were previously reported as gene candidates for isolated tooth agenesis." (PMID 34545288, 2021). "The aim of the present study was to identify the mutations in the candidate genes, PAX9, MSX1 and WNT10A, responsible for tooth agenesis in 4 Iranian families with hereditary pattern of non-syndromic tooth agenesis." (PMID 33014315, 2020). "Candidate genes, such as PAX9, MSX1, AXIN2, and EDA, are related to etiology of tooth agenesis." (PMID 25215247, 2014). "The molecular mechanism of human tooth agenesis mediated by MSX1 mutation is however independent of PAX9, since most MSX1 mutations related to oligodontia can potentiate PAX9-induced Bmp4-promoter activation." (PMID 25101640, 2014). "MSX1, PAX9, AXIN2, WNT10A, and EDA are proven candidate genes for familial tooth agenesis." (PMID 23227268, 2012). "All variants were analyzed based on bioinformatics websites and Iranian gene databases, and as a result, it was revealed that variants of PAX9, MSX1 and WNT10A may not play a role in non-syndromic tooth agenesis among Iranian cases." (PMID 33014315, 2020). "In conclusion, the variants found in the PAX9, MSX1 and WNT10A genes may not play a role in nonsyndromic tooth agenesis, but further studies should be performed to explore the exact association between these SNPs and the disease." (PMID 33014315, 2020).
tooth agenesis (continued). "However, among those 119 sequence variants a c.956G>T mutation in X-linked EDA1 was the unique one among six candidate genes (viz.PAX9, MSX1, AXIN2, WNT10A, EDAR and EDA1) associated with non-syndromic tooth agenesis known so far." (PMID 25203534, 2014). "We found that PAX9-related NSO accounted for 78.2% of the 193 patients, non-syndromic hypodontia for 18.1%, and syndromic oligodontia account for 2.6%." (PMID 37056289, 2023). "In another pedigree investigated in this study, we identified one sporadic hypodontia case with a unilateral cleft lip and palate, but no MSX1 or PAX9 gene variations were detected." (PMID 25101640, 2014).